TOP1 (DNA topoisomerase I)
Diseases named in the same sentence as TOP1 in open-access papers (continued):
Sharing a sentence is not in itself a finding about the gene and the disease.
cancer (continued). "Given that TOP1 is essential for cell growth, whether N722D and N722K mutations maintain growth advantages for cancer cells is unclear and requires further investigation." (PMID 36114357, 2022). "We report here the synthesis of novel thymine biomimetic photo-adducts bearing an alkane spacer between nucleobases and characterized by antimelanoma activity against two mutated cancer cell lines overexpressing human Topoisomerase 1 (TOP1), namely SKMEL28 and RPMI7951." (PMID 35055101, 2022). "Similarly, CPT-resistant mutations in the TOP1 gene have also been discovered in human cancer cell lines that were generated as CPT-resistant lines in vitro, namely, R346H and D533G16." (PMID 33833336, 2021). "The screening revealed two candidates, and further characterization of these substances, namely, berberine and coptisine, found that these compounds might act against cancer cells with CPT-resistant TOP1 mutations." (PMID 33833336, 2021). "It is unknown if highly active Top1 variants exist in certain cancer cells and help evade the tumor growth‐curtailing the effects of doxorubicin." (PMID 32134564, 2020). "We therefore hypothesized that a higher Top1 level in cancer cells is associated with more toxic effects of irinotecan." (PMID 32326511, 2020). "In recent years, studies have shown that Top1 poisons and nucleoside analogs together with other anti-cancer drugs such as cisplatin cause replication stress and the DNA repair pathways that modulate the cytotoxic activities of these compounds are being elucidated." (PMID 31930190, 2019). "However, to date, very little research has been done to evaluate the connection between TOP1 activity and cancer risk." (PMID 27181710, 2016). "In this study, the results revealed an association between TOP1 expression and cancer progression." (PMID 26207989, 2015). "However, the TOP1 inhibitor topotecan causes cytotoxicity against non-cancer cells." (PMID 41276688, 2025). "Beyond cancer treatment, macroH2A1.1 may protect from repeated TOP1 cleavage, particularly at actively transcribed genes, which were recently shown to accumulate a unique TOP1 mutation signature that contributes to mutagenesis and malignant transformation." (PMID 40796804, 2025). "Nearly half of protein-coding associated mutations of the Top1 mutated gene GATA3 (128/261) occurred in BRCA while the protein-coding associated mutations of 9 other genes tened to be evenly distributed across all the cancer types with a major pattern of missense mutation." (PMID 37917664, 2023). "Thus, identifying WRN deficiency in individual cancer patient may help in achieving better and predictable prognosis through TOP1 inhibitor‐based personalized/targeted therapy." (PMID 35582959, 2022). "Loss of genomic stability once TOP1 is suppressed may therefore drive cancer development." (PMID 24103454, 2013). "Strikingly, combining PRMT5 inhibitors (PRMT5i) with Top1 poisons such as irinotecan enhances cytotoxicity across multiple cancer cell types." (PMID 42216760, 2026). "Our results define PRMT5-driven Top1 arginine methylation as a crucial regulatory mechanism and highlight PRMT5i as a means to potentiate Top1-based cancer treatment." (PMID 42216760, 2026). "Camptothecin and its derivatives serve as crucial chemotherapeutic agents in clinical cancer treatment, owing to their unique inhibitory activity against DNA topoisomerase I (TOP1)." (PMID 42293686, 2026). "In human cancers, Top1 can be targeted by anticarcinogenic drug camptothecin (CPT) and its analogs including irinotecan and topotecan." (PMID 41009588, 2025). "Topoisomerase 1 (Top1) is considered an ideal target for cancer therapy owing to its critical role in modulating the degree of DNA supercoiling." (PMID 40141117, 2025). "TAS‐103 is an indeno‐quinoline derivative used in cancer research and has been reported to inhibit DNA topoisomerase I/II." (PMID 40371758, 2025).
cancer (continued). "This function has clinical implications for therapeutic regimen involving TOP1 inhibition and points to macroH2A1.1 as a predictive marker for cancer cell sensitivity to TOP1 poisons." (PMID 40796804, 2025). "DNA topoisomerase I (TOP1) is overexpressed in various cancers and plays a role in promoting DNA replication and cell division, thereby stimulating tumor growth." (PMID 40519928, 2025). "The blockage of the Top1 can be important for the inhibition of cancer cell growth during the drug treatment; and camptothecin." (PMID 39264927, 2024). "Our current findings suggest that TOP1 inhibitors represent attractive candidates capable of enhancing the efficacy of cancer immunotherapy." (PMID 38564022, 2024). "The DNA topoisomerase can function as an established cancer target because Human Topoisomerase (Top1) regulates genetic transcription during the post-mitotic phase and plays a critical role in DNA supercoiling during replication and repair." (PMID 39264927, 2024). "A mechanism employed by cancer cells to resist killing by TOP1 poisons is the overexpression of enzymes capable to repair TOP1-DNA breaks, such as tyrosyl-DNA-phosphodiesterase 1 (TDP1)." (PMID 39109293, 2024). "Among the antiproliferative compounds studied for cancer therapy, it is worth highlighting the inhibitors of TOP1, an overexpressed target enzyme in tumor cells." (PMID 39770084, 2024). "This regulatory effect of TOP1 on cGAS and PD-L1 in vivo reinforces the potential of TOP1 as a therapeutic target and illustrates the intricate interplay of cellular signaling in cancer progression." (PMID 39156107, 2024). "The content of TOP1 is much higher in cancer cells than in normal tissue, especially at the G2/M stage." (PMID 38783957, 2024). "We further extended the importance of TOP1 up-regulation to other cancers by examining TOP1 mRNA levels in the same 44 patient tissues (22 paired NTs and tumors) from breast, colon, and liver tissues that were used for DoG RNA calling from TCGA." (PMID 38959318, 2024). "The use of topoisomerase (TOP1) poisons can kill cancer cells through the trapping of TOP1 on DNA, leading to lethal DNA double-strand breaks." (PMID 39109293, 2024). "FAM111A can protect cancer cells from chemotherapeutic drugs such as TOP1 inhibitors, which generate DPCs containing stabilized TOP1ccs10." (PMID 38453899, 2024). "As Top1-mediated genomic lesions can disrupt DNA replication and subsequently inhibit cellular proliferation of cancer cells, Tdp1 inhibitors have been developed as potential cancer therapies." (PMID 39338235, 2024). "Given the importance of TOP1 inhibition in cancer therapy, the role of TDP1 in TOP1-DPCR has been extensively investigated in vitro and in cell cultures, but data on the vertebrate models are sparse." (PMID 37788708, 2023). "Gefitinib in combination with DNA topoisomerase I inhibitor CPT-11 exerts a powerful anti-cancer effect via the activation of apoptosis and the inhibition of EGFR phosphorylation in vitro and in vivo." (PMID 36768961, 2023). "The elevated expression of TOP1 in various tumor cell types makes it an important drug target for anti-cancer therapy." (PMID 37689760, 2023). "The simultaneous targeting of BRD4 and TOP1 with a panel of BET inhibitors and TOP1 poisons, respectively, synergistically inhibited cancer cell growth in vitro." (PMID 37831776, 2023). "Camptothecin (CPT), first isolated from Chinese tree Camptotheca acuminate, produces rapid and prolonged inhibition of DNA synthesis and induction of DNA damage by targeting topoisomerase I (top1), which is highly activated in cancer cells." (PMID 36675143, 2023). "Camptothecin (CPT) is a cytotoxic alkaloid that inhibits cancer cell replication by interfering with the DNA topoisomerase 1 (Top1)." (PMID 36674567, 2023). "Top1 enzyme expression in cancer cells is significantly higher than in healthy cells, allowing CPT targeted selectivity." (PMID 36674567, 2023).
cancer (continued). "Increased sensitivity of cells with reduced PARP1 activity to the TOP1 inhibitor camptothecin, irinotecan and topotecan, which is used as a cancer therapeutic agent, raised a potential combinatorial treatment of TOP1i with PARPi." (PMID 37554969, 2023). "Examples of TOP1-targeting anti-cancer drugs include the water-soluble camptothecin (CPT) derivatives, topotecan, and irinotecan." (PMID 37242440, 2023). "This puzzling feature is probably related to genetic instability in cancer, which generates additional Top1 cleavage sites during cancer evolution towards advanced stages, thus making cells more sensitive to irinotecan." (PMID 37240063, 2023). "Our data indicate that MUS81 and TDP1 play independent roles in the repair of CPT-induced lesions, thus representing new therapeutic targets for cancer cell sensitisation in combination with TOP1 inhibitors." (PMID 37194054, 2023). "DS-8201 is a novel HER2-targeted antibody–drug conjugate incorporating a DNA topoisomerase I inhibitor, which has anti-cancer efficacy in clinical trials and anti-tumor immunity in mouse models." (PMID 37013547, 2023). "One of the classes of drugs that are frequently used in cancer therapy is inhibitors of DNA supercoil relaxing topoisomerases, including Top1 and Top2." (PMID 37108395, 2023). "TOP1 inhibitors are significant compounds for their anti-cancer, anti-bacterial, and anti-parasitic capacity." (PMID 37242440, 2023). "Benzophenanthridine alkaloids are capable of affecting the activity of DNA topoisomerase I and topoisomerase II, suppressing the rapid proliferation of tumor cells, inducing cancer cells ferroptosis, inhibiting the growth of tumor stem cells, and so forth." (PMID 37764364, 2023). "HCPT, a specific inhibitor of TOP1, has shown profound anti-cancer effects with relatively low toxicity." (PMID 37689760, 2023). "Repair of topoisomerase 1 (TOP1) DNA protein crosslinks (DPC) limits the efficacy of the TOP1 inhibitor irinotecan in cancer therapy." (PMID 37353483, 2023). "TDP1 appears as a target in cancer drug design owing to its ability to sensitize tumor cells to the action of TOP1 poisons and to break down various DNA adducts induced by chemotherapeutics." (PMID 36982223, 2023). "The US National Cancer Institute screening program identified CPT as a promising therapeutic agent for the treatment of cancers because it specifically targets topoisomerase I (top1), which is highly activated in cancer cells." (PMID 36675143, 2023). "Top1 is the sole target of the widely used anti-cancer chemotherapeutic camptothecin (CPT) and its derivatives including irinotecan and topotecan." (PMID 35291312, 2022). "Although the efficacy of cancer therapy with TOP1 inhibitors has been greatly enhanced with the TOP1-ADCs, there remains ample room for improvement in the therapeutic efficacy of the TOP1-ADC conjugates." (PMID 36015333, 2022). "It has also been shown that WS patient cells or WRN‐depleted cancer cells are hypersensitive to TOP1 inhibitors due to defective S‐phase checkpoint and repair." (PMID 35582959, 2022). "MYCL1, (MYCL proto-oncogene, BHLH transcription factor), and TOP1 (DNA topoisomerase 1) have been suggested to play a role in various types of cancer." (PMID 35659227, 2022). "TDP1 inhibitors can potentiate the combined anticancer activities of Top1-target anticancer drugs and overcome cancer cell resistance to therapeutic drugs in some cancers." (PMID 35323510, 2022). "It is likely that our mechanistic investigation of these pathways will contribute to the development of combinational TOP1-inhibitor–based cancer therapies." (PMID 35869071, 2022). "Understanding the mechanism of differential responses to TOP1 blockade and identifying the predictive markers for cancer cell sensitivity will help further TOP1-targeted therapy for TNBC treatment and improve the clinical use of TOP1 inhibitors." (PMID 35844787, 2022).
cancer (continued). "We further summarized six genes (IGF2BP3, LYAR, RALY, STAU1, SYNCRIP, and TOP1) that displayed high correlations between mRNA and protein expression in both cancer and cell line databases." (PMID 36428700, 2022). "Camptothecin (CPT) is a specific inhibitor of the DNA topoisomerase I (Top1p), currently used in cancer therapy, which induces DNA damage and cell death." (PMID 35071999, 2022). "Several studies have also shown that TOP1 inhibition‐mediated DNA damage triggers NF‐κB, a transcription factor, to induce prosurvival signaling, leading to resistance in different cancers." (PMID 35582959, 2022). "Tyrosyl-DNA phosphodiesterase 1 (TDP1) is believed to be responsible for making cancer cells resistant since this enzyme cleaves the TOP1–DNA covalent complex, thereby repairing DNA damage mediated by TOP1 poisons." (PMID 35684313, 2022). "Here we investigated how CPT-resistance conferring Top1 mutants, which emerge in cancer patients and cells treated with CPT, affect G4-induced genomic instability in S. cerevisiae." (PMID 35291312, 2022). "The high conservation between yeast and human C-terminal domains of Top1 allowed us to measure the effect of C-terminal Top1 mutants found in CPT-resistant human cancer cells on G4-induced instability by expressing the analogous mutants in yeast." (PMID 35291312, 2022). "Taken together, our findings demonstrate that TOP1 poisoning by CPT and LMP776 can induce micronuclei in the studied human cancer cells at similar levels, and that R-loops play a mechanistic role in micronuclei formation and DNA damage induced by TOP1 poisons." (PMID 35794238, 2022). "Such TOP1-mediated deletions occur somatically in cancer, and the ID-TOP1 signature is also found in physiological settings, contributing to genic de novo indel mutations in the germline." (PMID 35140396, 2022). "i) Although TOP1 is highly expressed in cancer cells, TOP1 CAD-seq is designed to select only TOP1 molecules covalently engaged with the DNA, which represent a fraction of the total protein level." (PMID 35942340, 2022). "The findings reported here are clinically relevant since Top1 mutants arise in cancer cells in response to treatment with CPT or CPT-derivatives and human nucleolin is frequently overexpressed or mis-regulated in cancer cells." (PMID 35291312, 2022). "Due to their selectivity as topoisomerase I (TOP1) inhibitors that trap TOP1 cleavage complexes, camptothecin and its derivatives are promising anti-cancer drugs." (PMID 36015333, 2022). "It remained to determine how the expression of catalytic or DNA binding Top1 mutants found in CPT-resistant cancer cells would affect DNA aberrations at G4s." (PMID 35291312, 2022). "Here, we have uncovered aspects of micronuclei formation by TOP1 poisons in cancer cells and the molecular defects of human SCLC that largely impair innate immune gene activation by TOP1 poisons." (PMID 35794238, 2022). "Strategies to modify chemical structures of TOP1 inhibitors to generate stabilized and persistent TOP1cc showed enhanced sensitivity of cancer cells in vitro and in vivo." (PMID 35582959, 2022). "In summary, we have found that expression of Top1 mutants, some of which are found in CPT-resistant cancer cells, sharply increases the genomic instability associated with co-transcriptionally-formed G4s in yeast." (PMID 35291312, 2022). "Camptothecin (CPT) derivatives, for example, topotecan and irinotecan specifically inhibit Topoisomerase 1 (TOP1) and are clinically approved chemotherapeutics for a wide array of cancers including ovarian, colorectal and lung cancers." (PMID 35582959, 2022). "Further research on various anticancer drugs and cancer cell targets is needed to identify additional candidates for combination with TOP1 inhibitors." (PMID 36015333, 2022). "In the future, it will be valuable to explore how CPT-treatment and subsequent emergence of Top1 mutants can lead to further genome instability and potential secondary cancers." (PMID 35291312, 2022).
cancer (continued). "TOP1 inhibitors have shown considerable potential as therapeutic agents against cancers; however, their clinical application has been hindered by their adverse pharmacokinetic profiles and off-target toxicities." (PMID 36015333, 2022). "DNA topoisomerase IB (Top1) is overexpressed among various cancer cell lines and is widely considered an essential nuclear enzyme that regulates DNA topology structure in several cellular metabolic processes including replication and transcription." (PMID 35164276, 2022). "Some copper complexes inhibit either or both Top1 and Top2 and results in severe DNA damage, cell cycle arrest, and death in cancer cells." (PMID 35280788, 2022). "Here, we review the importance of TOP1 inhibitor-based ADCs (TOP1-ADCs) in cancer therapy, the current state of knowledge regarding the design of TOP1-ADCs, and TOP1-ADCs under development." (PMID 36015333, 2022). "Camptothecin is one of the most powerful alkaloids for cancer therapy due to its unique affinity for binding with DNA topoisomerase I, blocking its various biological processes: DNA replication, RNA transcription and chromatin assembly." (PMID 35566384, 2022). "In agreement with a previous report on G-quadruplex binders and micronuclei in mammalian cancer cells, abolishing TOP1 poison-mediated increase of R-loops by RNaseH1 overexpression drastically reduced micronuclei levels." (PMID 35794238, 2022). "In the present work, we have shown for the first time that a derivative of a nucleoside inhibiting Tdp1 sensitizes mice Krebs-2 ascitic carcinoma cells to the action of the Top1 inhibitor Tpc used in the clinic." (PMID 36615517, 2022). "These mimics alter the activity of DNA interacting enzymes used as targets for cancer treatment, such as DNA topoisomerase I, and they are cytotoxic only in the presence of a transfection agent." (PMID 34203395, 2021). "Topotecan (TPT), a water-soluble camptothecin analog that inhibits the catalytic activity of DNA topoisomerase I, is a widely used anticancer drug against various cancers, including ovarian, lung, and other cancers." (PMID 33921129, 2021). "This review outlines the mechanism of PARP activation, molecular networks of PARP1 for the repair of Top1-induced DNA breaks, and the rationale for the combination of PARP and Top1 poisons in cancer." (PMID 33981998, 2021). "Hydroxycamptothecine (IC50 = 6.87 ± 0.77 × 10−6 M) and its stereoisomer S-10-Hydroxycamptothecine (IC50 = 7.22 ± 0.06 × 10−6 M) are DNA topoisomerase I inhibitors with anti-cancer activity." (PMID 34194331, 2021). "Concerning combination therapy, PARP inhibitors synergize with DNA base alkylating agents, cisplatin and Top1 poisons in cancers." (PMID 33981998, 2021). "This suggests that identification of small molecules that stabilize the Tdp1cc similar to the Top1 and Top2 poisons would offer a novel therapeutic strategy in the fight against cancer." (PMID 34532656, 2021). "CPT and its derivatives target mammalian Top1 enzymes and are currently one of the most effective new anti-cancer drugs with good therapeutic effects on a variety of malignant tumors." (PMID 34439157, 2021). "Synthetic lethality for the PARP inhibitors and platinum derivatives in HRD cancers is being applied for cancer treatment and recent studies in animal models suggest such synthetic lethality for TOP1 inhibitors." (PMID 34572827, 2021). "The mechanism of the anti-cancer activity of SN-38 is the stabilization of the DNA Top1-DNA cleavable complex in cancer cells, resulting in the arrest of DNA replication." (PMID 35582377, 2021). "This indicates that low doses of all three TDP1 inhibitors can kill cancer cells when combined with a low dose of TOP1 poison." (PMID 34300575, 2021). "In eukaryotic cells, the type IB topoisomerase, topoisomerase 1 (TOP1) is an interesting target of anti-cancer or anti-parasitic drugs." (PMID 34452216, 2021).